CD200 (CD200 molecule)
Diseases named in the same sentence as CD200 in open-access papers (continued):
Sharing a sentence is not in itself a finding about the gene and the disease.
hairy cell leukemia (9 papers, 2012 to 2023). Hairy cell leukemia (HCL) is a rare type of leukemia in which abnormal B-lymphocytes are present in the bone marrow, spleen and peripheral blood. "In this context, CD200 has been shown to have differential expression in B-cell neoplasms and to well discriminate CLL from MCL and hairy cell leukemia (HCL) and its variant form (v-HCL)." (PMID 33324560, 2020). "Staining for CD200 is positive but with a lower intensity than in hairy cell leukemia." (PMID 37656249, 2023). "Furthermore, all 5 cases of hairy cell leukaemia (HCL) expressed CD200." (PMID 37822353, 2023). "Finally, and consistent with data in MM and CLL, overexpression of CD200 was described in cases of both Hairy Cell leukemia (HCL), ALL and AML and correlated with prognosis for this disease." (PMID 33562512, 2021). "Besides, hairy cell leukemia (HCL) samples showed bright CD200 expression in a homogenous pattern, indicating that CD200 may help differentiate HCL from other CD5 negative mature B cell neoplasms." (PMID 26910908, 2016).
Arthritis (8 papers, 2012 to 2026). Inflammation of a joint. "Consistent with our previous observations in mice and humans, we observed an increase in CD2+MHC-II+CCR2+ myeloid precursors and a significant decrease in CD200+ fibroblasts in the synovial tissue during the onset of arthritis in humans." (PMID 41482544, 2026). "After treatment with agonistic anti-CD200R1, arthritis was significantly reduced on day 21, supporting the critical anti-inflammatory signaling mediated by CD200." (PMID 41482544, 2026). "After blocking CD200, initially arthritis-resistant animals developed joint inflammation on day 21, supporting the critical gate-keeping role of CD200+ fibroblasts interacting with migrating CD2+MHC-II+CCR2+ myeloid precursors." (PMID 41482544, 2026). "Rather, the local microenvironment, particularly CD200+ fibroblasts, acted as gatekeepers of arthritis, engaging the checkpoint receptor CD200R1 on migrating CD2+MHC-II+CCR2+ myeloid precursors." (PMID 41482544, 2026). "Collectively these findings suggest that arthritis is controlled not only by the migration of CD2+MHC-II+CCR2+ myeloid precursors from the skin to the joint but also by CD200+ fibroblasts in the joint." (PMID 41482544, 2026). "Conversely, blocking CD200 in different arthritis-resistant models resulted in the onset of arthritis, highlighting the inflammatory potential of these skin-derived myeloid precursors." (PMID 41482544, 2026). "This process is associated with the emergence of a pro-resolving network built around a CD200-expressing fibroblast phenotype that is also present in human arthritis during the resolution phase." (PMID 39586916, 2025). "Consistent with previous reports, the data show that administration of CD200-Fc, which mimics the effects of pro-resolving fibroblasts, controls inflammation and tissue damage in experimental arthritis." (PMID 39586916, 2025). "Fourth, we used IL-23OE in the arthritis-susceptible BALB/c inbred strain and intervened every 5 days with an agonistic anti-CD200R1 treatment (OX-110) starting on day 7 to restore the suppression of skin-derived precursors by resident CD200+ fibroblasts." (PMID 41482544, 2026). "Thus, CD200-Fc may provide a new therapeutic option to efficiently promote a pro-resolving environment in the joint and allow to restore tissue homeostasis in arthritis." (PMID 39586916, 2025). "Second, we used IL-23OE in the arthritis-resistant C57BL/6 inbred strain and intervened every second day with anti-CD200 treatment (OX-90) to block the suppression of skin-derived precursors by resident CD200+ fibroblasts." (PMID 41482544, 2026). "In all three analyses, samples of CD200+ cells from mice with arthritis and non-immunized (NI) mice group together." (PMID 33304967, 2020). "Consequently, intervention with an antibody to CD200 polarized CD2+MHC-II+CCR2+ myeloid precursors toward a proinflammatory phenotype in vitro and allowed the in vivo spreading of psoriatic disease from the skin to the joints even in initially arthritis-resistant mice." (PMID 41482544, 2026). "We then used imaging mass cytometry (IMC) to detect CD2+MHC-II+CCR2+ myeloid precursors and CD200+ (DKK3+FAP+CD45−CD31−) fibroblasts in the synovial tissues of individuals with early PsA who had just developed arthritis and individuals with psoriasis without arthritis." (PMID 41482544, 2026).
Autoimmunity (8 papers, 2005 to 2023). The occurrence of an immune reaction against the organism's own cells or tissues. "All these data imply that the dysregulation of the CD200/CD200R axis may affect autoimmunity and inflammation." (PMID 32967175, 2020). "In this context, several studies to date have shown that the CD200:CD200R1 pathway exhibits an immunosuppressive effect on the inflammatory cellular response and contributes to the reduction of severity in animal models of inflammation and autoimmunity." (PMID 30195773, 2018).
experimental autoimmune encephalomyelitis (8 papers, 2012 to 2022). An autoimmune demyelinating disease of the central nervous system that is produced experimentally in animals by the injection of homogenized brain or spinal cord in Freund's adjuvant. "Previous studies have reported that CD200-deficient mice show an accelerated microglial response that results in a more rapid onset of experimental autoimmune encephalomyelitis." (PMID 32257540, 2020). "Conversely, CD200−/− mice have been shown to display myeloid cell dysregulation, enhanced susceptibility to experimental autoimmune encephalomyelitis, and microglial activation." (PMID 26891688, 2016). "Accordingly, CD200-knockout animals demonstrated chronic inflammation of the central nervous system (CNS), the onset of experimental autoimmune encephalomyelitis, and showed higher susceptibility to autoimmune reactions due to impaired CD200–CD200R interaction in response to injury." (PMID 35326506, 2022). "It has been demonstrated that mice with levels of CD200 increased by spontaneous mutation in the Wld gene have less activated monocytes and increasing expression of IL-10 in the central nervous system following induction of experimental autoimmune encephalomyelitis." (PMID 26891688, 2016). "Moreover, an increased expression of IL-10 in relation to enhanced neuronal levels of CD200 has been also found in the central nervous system of experimental autoimmune encephalomyelitis mice." (PMID 26891688, 2016). "Faster and more pronounced inflammatory responses are observed in absence of CD200 in model of experimental autoimmune encephalomyelitis and an increased susceptibility to collagen-induced arthritis, whereas treatment with recombinant CD200 reduces disease severity in both models." (PMID 36591265, 2022).
head and neck squamous cell carcinoma (7 papers, 2019 to 2026). A squamous cell carcinoma that arises from any of the following anatomic sites: lip and oral cavity, nasal cavity, paranasal sinuses, pharynx, larynx, and salivary glands. "The expression of CD200 has been associated with the characteristics of cancer stem cells shown in head and neck squamous cell carcinomas, and also with the reduced chemosensitivity and radiosensitivity of these cancers." (PMID 39795972, 2024). "The expression of CD200 in head and neck squamous cell carcinoma was associated with characteristics similar to cancer stem cells and with the resistance to chemotherapy and radiation." (PMID 39795972, 2024). "CD200 expression in head and neck squamous cell carcinomas is related to features typical of cancer stem cells." (PMID 39795972, 2024). "Recently, mice transplanted with head and neck squamous cell carcinoma (HNSCC) cells overexpressing CD200 exhibited attenuated tumor growth when treated with adenovirus-expressing soluble CD200R-Ig." (PMID 37894750, 2023). "Here, we investigated whether CD200 expression, which is enriched mainly in high-grade head and neck squamous cell carcinoma (HNSCC), correlates with cancer progression, particularly the epithelial-to-mesenchymal transition (EMT)." (PMID 31627350, 2019). "More recent findings in another human xenograft model of head and neck cancers showed that in mice transplanted with head and neck squamous cell carcinoma (HNSCC), cells overexpressing CD200 had attenuated tumor growth when treated with adenovirus-expressing soluble CD200R-Ig." (PMID 38540350, 2024). "Moreover, ectopic CD200 expression induces EMT-related genes, enhanced resistance to radiotherapy, and invasiveness in head and neck squamous cell carcinoma and skin tumors." (PMID 32120774, 2020).
lymphoma (7 papers, 2016 to 2024). A malignant (clonal) proliferation of B- lymphocytes or T- lymphocytes which involves the lymph nodes, bone marrow and/or extranodal sites. "A phase I clinical trial reported a positive response to anti‐CD200 therapy in a mixed population of lymphoma/leukemia cancer patients." (PMID 26725371, 2016). "Additionally, blocking CD200 increased the killing of CD200+ lymphoma cells and CLL patient cells by CD8+ cytotoxic T lymphocytes in vitro." (PMID 37894750, 2023). "For NOD/SCID mice injected with human lymphoma cells expressing CD200 and treated with an anti-CD200 antibody without effector functions, i.e. a ‘pure’ blocking antibody, there was superior tumour growth inhibition versus an antibody with effector functions." (PMID 37082107, 2023). "For example, CLL/SLL cells are positive for CD5, CD23, CD200, dim for CD20 and CD81, and negative for FMC-7; in MCL, lymphoma cells are positive for CD5, and negative for CD23; and in FL, lymphoma cells are positive for CD10 and CD20, and negative for CD34 and TdT." (PMID 34879826, 2021).
asthma (6 papers, 2021 to 2025). "Dysregulation of CD200 in asthma has been confirmed by several studies evaluating CD200 expression in PBMCs of asthmatic patients or serum levels of soluble CD200 which is probably produced by membrane shedding or mRNA splicing during asthma pathogenesis." (PMID 36865540, 2023). "In asthma, CD200 expression is reduced in peripheral blood cells of patients with asthma during exacerbation, and pharmacological modulation of this receptor has been shown to improve clinical and inflammatory outcomes in preclinical asthma models." (PMID 36865540, 2023). "In this work, both MKP1 and CD200 expression were significantly lower in neutrophils of severe asthma and COPD patients than in neutrophils from healthy subjects." (PMID 35332239, 2022). "Importantly, CD200R engagement on ILC2 using CD200-Fc chimeric protein in humanized mouse models of asthma dampened airway resistance, reduced eosinophilia and improved pulmonary dynamic compliance." (PMID 36865540, 2023). "The expression of CD-200 and MKP-1 were downregulated in neutrophils from severe asthma and COPD patients while GRα was not modified." (PMID 35332239, 2022).
neuroblastoma (6 papers, 2017 to 2025). Neuroblastoma (NB) is the most common solid, extracranial childhood tumor. "The specific mechanisms by which CD200 expression impacts these cancers are linked to immune modulation and evasion, as seen in neuroblastoma." (PMID 38927907, 2024). "High expression levels of CCL2, CCL4, CCL21, CD200, CXCR3, and IGSF6 were significantly associated with improved survival in neuroblastoma patients (all p < 0.001)." (PMID 40718780, 2025). "CD200 expression in neuroblastoma tumors plays a role in regulating the composition of these immune cells and impacting the anti-tumor immune response within TME." (PMID 38927907, 2024). "For example, neuroblastoma tumors exhibit elevated levels of the immune checkpoint molecule CD200, which interacts with its corresponding receptor CD200R." (PMID 38927907, 2024). "Moreover, CD200 was overexpressed in pediatric neuroblastoma tumors." (PMID 33804482, 2021). "Our study demonstrates that tertiary lymphoid structure (TLS)-related genes play a crucial role in neuroblastoma (NB) prognosis, with a 6-gene TLS signature (CCL2, CCL4, CCL21, CD200, CXCR3, and IGSF6) serving as a promising prognostic biomarker for NB." (PMID 40718780, 2025).
ovarian carcinoma (6 papers, 2012 to 2025). A malignant neoplasm originating from the surface ovarian epithelium. "Through single-cell analysis, we further identified five potential prognostic biomarkers associated with the ovarian cancer cell functional pathway and TIME: three risk genes PI3, AUP1 and CCDC80 and two protective genes CD200 and GNAS." (PMID 40534859, 2025). "Through integrated machine learning and single-cell analysis, we identified five prognostic-associated SRGs (PI3, AUP1, CD200, GNAS and CCDC80) regulated by global SUMOylation levels in ovarian cancer." (PMID 40534859, 2025). "On the whole, our study identified five key SRGs, including the risk genes AUP1, PI3 and CCDC80, as well as the protective genes CD200 and GNAS and elucidated their prognostic potential in ovarian cancer." (PMID 40534859, 2025). "In the present study, both univariate Cox regression analysis and integrated machine learning approaches identified CD200 and GNAS as protective biomarkers in ovarian cancer." (PMID 40534859, 2025). "MSLN was positively correlated with immunosuppressive genes in ovarian cancer, such as LGALS9, CD276, TMIGD2, CD200, TNFRSF14, and human leukocyte antigen (HLA)-related families including HLA-DRA, HLA-DRB1, HLA-DPA1, HLA-DMA, HLA-E, etc.." (PMID 35692779, 2022). "However, the mechanisms through which CD200 and GNAS influence ovarian cancer prognosis remain unclear and require further investigation through in vitro and in vivo experiments." (PMID 40534859, 2025).
pancreatic cancer (6 papers, 2021 to 2024). "This study highlights the importance of CD200 expression in pancreatic cancer and provides the rationale for designing novel therapeutic strategies that target this protein." (PMID 38619621, 2024). "The expression of CD200 in the pancreatic cancer microenvironment can amplify MDSCs, and targeting CD200 can enhance the activity of checkpoint immunotherapy." (PMID 36359832, 2022). "Although stromal CD200R expression appeared uniform, as expected, across different tumor types, we measured elevated levels of CD200 within the tumor compartment in patients with lung and pancreatic cancer." (PMID 33804482, 2021). "This work demonstrates the potential clinical utility of CD8 and FAP in PDAC patients, and it sheds light on the expression patterns of CD200 in pancreatic cancer as the protein is being tested as a target for immune checkpoint blockade." (PMID 34771664, 2021). "Our laboratory previously reported that CD200 is overexpressed in patients with PDAC and that blockade of CD200 in a murine subcutaneous and genetically engineered mouse models reduced tumor burden, suggesting a pro-tumor role for CD200 in the context of pancreatic cancer." (PMID 38619621, 2024). "Whatsmore, CD200 has been shown to promote immunosuppression in the pancreatic tumor microenvironment and targeting CD200 may enhance activity of checkpoint immunotherapy." (PMID 35330729, 2022). "In the context of pancreatic cancer, we have previously reported that CD200 is expressed in the pancreatic tumor microenvironment (TME), and that targeting CD200 in murine tumor models reduces tumor burden." (PMID 38619621, 2024). "Lastly, CD200 was expressed in the stroma in the majority of these PDAC patients, and blockade of this protein could be another potential route for treating pancreatic cancer patients." (PMID 34771664, 2021). "Although we found no prognostic significance of CD200 in this cohort of pancreatic cancer patients, this does not rule out the potential predictive value of this marker, as the protein is being investigated for immune checkpoint blockade drugs." (PMID 34771664, 2021). "Future staining of invasive edges for CD200 expression may reveal whether or not CD200 plays a role for pancreatic cancer invasion and progression." (PMID 38619621, 2024). "Here, we did not observe any differences in CD200 expression on CD8 + T cells; furthermore, we previously reported that dual blockade of CD200 and PD-1 further reduces tumor burden in a subcutaneous pancreatic tumor model." (PMID 38619621, 2024).
Parkinson disease (6 papers, 2007 to 2022). A progressive degenerative disorder of the central nervous system characterized by loss of dopamine producing neurons in the substantia nigra and the presence of Lewy bodies in the substantia nigra and locus coeruleus. "The CD200 gene is expressed in hair follicle stem cells, and is related to schizophrenia-like alterations in animals, in addition to Parkinson’s disease." (PMID 34679946, 2021). "Reduced CD200/CD200R interactions between neurons and microglia may contribute to Parkinson and Alzheimer pathogenesis via activation of microglial NADPH oxidase." (PMID 21975039, 2011). "In addition, the lack of CSF-1 does not appear to affect CD200 expression by neurons but we did note a decrease in the substantia nigra of op/op and WT mice, suggesting that this may be a mechanism by which microglia control may be attenuated in this specific area during Parkinson's disease." (PMID 18093340, 2007).
alopecia (5 papers, 2013 to 2024). Hair loss usually from the scalp. "In a CD200-deficient skin model, hair follicles showed inflammation that caused immune-mediated alopecia, correlating to a mouse model showing that CD200 knockdown mice suffer from peri- and intrafollicular inflammation and terminally scarring alopecia." (PMID 29333153, 2017). "We observed reduced CD200 positivity and increased T cells around HFs in mice with alopecia, indicating the collapse of HFIP, and a HF phase shift from anagen to telogen." (PMID 39450167, 2024). "Lesioned human scalp shows upregulation of MHC class I and II and downregulation of CD200 in the bulge (HFSCs), corroborated by the deletion of CD200 that in a mouse model resulted in peri-follicular immune cell infiltration and subsequently alopecia." (PMID 34966743, 2021). "The percentage of HFs with CD200+stained epithelium in the mice with no alopecia (49.1 ± 20.1%) was significantly higher than that in the mice with alopecia (1.8 ± 1.0%) (p < 0.0001)." (PMID 39450167, 2024). "In addition, we found CD200+staining on epithelium of HFs and around HFs in the mice with no alopecia and diminished CD200+staining of epithelium of HFs and around HFs in the mice with alopecia." (PMID 39450167, 2024). "We also found reduced CD200 staining and increased CD3+T cells surrounding the HFs of mice with alopecia compared to the mice without alopecia, indicating HF Immune Privilege (HFIP) collapse." (PMID 39450167, 2024).